WNT7A (Wnt family member 7A)
Diseases named in the same sentence as WNT7A in open-access papers (continued):
Sharing a sentence is not in itself a finding about the gene and the disease.
MRKH syndrome (1 paper, 2015). "The discovery of a four-gene epistatic effect (AMH, PBX1, WNT7A and WNT9B) in MRKH syndrome provides novel information for the elucidation of the genetic mechanism underlying the etiology of MRKH syndrome." (PMID 26075712, 2015). "Multifactor dimensionality reduction (MDR) analysis revealed novel dimensional epistatic four-gene effects (AMH, PBX1, WNT7A and WNT9B) in MRKH syndrome." (PMID 26075712, 2015). "Recently, a valuable gene expression profile of in vitro cultured vaginal tissue from MRKH syndrome patients has identified dysregulation of MUC1, WNT7A, JAG1 and DLL1, emphasizing the critical role of canonical Wnt signaling and the NOTCH pathway." (PMID 26075712, 2015). "The best four-way interaction model indicated by MDR analysis supported the following novel and bold assumption that the dimensional interactions of AMH, PBX1, WNT7A and WNT9B may play a role in the etiology of MRKH syndrome during MD development." (PMID 26075712, 2015). "Notably, we found a novel dimensional epistatic four-gene effect (AMH, PBX1, WNT7A and WNT9B) in MRKH syndrome, providing novel data to contribute to the elucidation of the genetic mechanisms underlying its multifactorial etiology." (PMID 26075712, 2015).
nasopharyngeal carcinoma (1 paper, 2024). A carcinoma arising from the nasopharyngeal epithelium. "Moreover, in nasopharyngeal carcinoma, FSTL1 blocks Wnt7a inhibition of ERK phosphorylation, inducing MMP9 production, extracellular matrix degradation, and metastasis." (PMID 38605354, 2024).
neuroendocrine tumor (1 paper, 2023). "We observed a strong downregulation of Sstr2 expression in the Wnt7a expressing cells, indicating that Wnt signaling is also capable of downregulating endogenous Sstr2 expression in neuroendocrine tumor cells." (PMID 36965619, 2023). "To assess whether Wnts are capable of stimulating endogenous Sstr2 downregulation in neuroendocrine tumor cells, we stably overexpressed Wnt7a in IMR32 cells and then assessed endogenous Sstr2 expression by Western blotting." (PMID 36965619, 2023).
Obesity (1 paper, 2022). Accumulation of substantial excess body fat. "In the present study, skeletal muscle IGF‐1, Wnt3a, Wnt5a and Wnt7a mRNAs were all reduced in subjects with obesity." (PMID 35293040, 2022).
parenchymal hematoma (1 paper, 2021). A severe presentation of intracerebral bleeding. "We identified that several genetic variants of WNT7A and GPR124 are associated with risk of parenchymal hematoma (PH), the clinically detrimental form of HT." (PMID 32991049, 2021).
pterygium (1 paper, 2021). A wedge-shaped fibrovascular lesion arising from the bulbar conjunctiva and extending to the cornea. "WNT7A expression did not change in our datasets; however, two other genes encoding Wnt ligands—WNT7B and WNT9A—were upregulated in pterygium." (PMID 34769520, 2021).
renal dysfunction (1 paper, 2021). "This study has replicated APOL1 gene variants: (G1)-rs73885319 and (G2)-rs71785313, shown to be strongly associated with renal dysfunction in SCD patients, as well as A1CF-rs10994860, SYPL2-rs12136063, WNT7A-rs6795744, and TMEM60-rs6465825 in Cameroonian SCD patients." (PMID 33790942, 2021). "Moreover, these gene variants are enriched with the cartilage condensation process (P = 0.02976) in which WNT7A, revealed to be likely implicated in SCD patient renal dysfunction, is involved." (PMID 33790942, 2021).
serous carcinomas (1 paper, 2016). "When we reported the clinical significance of WNT7A during malignant transformation of OvCa, our results showed that WNT7A was highly expressed in serous carcinomas, the most common/aggressive subtype of OvCa." (PMID 27195958, 2016). "One of our findings clearly showed that high expression of WNT7A and FGF1 were correlated in OvCa, especially in serous carcinomas, and poor overall patient survival." (PMID 27195958, 2016).
uveitis (1 paper, 2018). An inflammatory process affecting a part of or the entire uvea. "As a homolog of WNT7B, WNT7A (ENSP00000285018) acts as one of the potential pathogenic factors of uveitis by interfering immune cell proliferation and maturation." (PMID 30349554, 2018). "According to recent publications, our inferred genes (WNT2, WNT16, WNT3, WNT7A, and WNT7B) are functionally related to the initiation and progression of uveitis due to their interference to the proliferation of urea and mixed immune cells." (PMID 30349554, 2018).
tumor (97 papers, 2006 to 2026). "In the same subclone we also observed an autocrine loop involving WNT7A - > FZD5 which has been previously linked to HGSOC tumour growth and progression." (PMID 38570491, 2024). "WNT7A is a member of the Wnt signaling pathway, which plays a crucial role in various biological processes, and it is closely associated with tumor initiation and progression." (PMID 37907576, 2023). "Expression of epithelial Wnts, such as Wnt7a/b, is also strongly reduced or lost suggesting that upon loss of Wnt secretion the repopulation of the tumor occurs via alternate cell types." (PMID 34849464, 2021). "WNT7A, a member of the family of 19 Wnt secreted glycoproteins, is commonly associated with tumor development." (PMID 32174831, 2020). "We also evaluated the effects of Wnt7a loss on other cellular tumor-suppressive mechanisms, such as apoptosis and autophagy." (PMID 25728679, 2015). "Furthermore, increased WNT7A expression was associated with a high tumor grade, increased depth of myometrial invasion, lymph node metastasis, and vascular invasion." (PMID 39188680, 2024). "Given the important role of Wnt/Wg signaling in tumor growth and progression, it can be foreseen that increasing Wnt7a could lead to the deleterious effects caused by promotion of tumor growth and progression." (PMID 34078667, 2021). "Conversely, we found that Wnt7a, a component of the Wnt/β-catenin pathway and the loss of which was previously reported to promote an undifferentiated tumor-protective phenotype in NSCLC, was markedly suppressed in the Gprc5a−/−Kras-mutant LUAD CSCs relative to parental cells." (PMID 31001473, 2019). "Although ovarian tumor cells are known to produce Wnt7a, it should be noted that tumor-associated macrophages may also be an important source of Wnt ligands that contribute to tumor progression." (PMID 26343197, 2015). "It is possible that smoking might decrease Wnt7A expression associated with tumor-associated macrophages." (PMID 25632963, 2015). "It was reported that progestogens upregulated Wnt7a gene expression in endometrial epithelial cells, suggesting that upregulation of Wnt7a may be associated with the tumor-suppressing effect of progestogens." (PMID 23304155, 2012). "Likewise, STAT4 could induce activation of tumor-associated fibroblasts (CAF) through tumor-derived Wnt7a, which promoted peritoneal metastasis of ovarian cancer through the EMT process." (PMID 36524006, 2022). "Wnt3a and Wnt7a are likewise upregulated in metastatic breast cancer cell lines in association with poor prognosis and inhibition of Wnt/β-catenin signaling via Wnt1 knockdown could efficiently suppress cell proliferation and tumor growth." (PMID 33585487, 2021). "Observations suggest that disruption of normal Wnt-7a expression by diethylstilbestrol and other estrogenic compounds leads to altered uterine cytoarchitecture and might be a mechanism ultimately causing neoplasia in the reproductive tract." (PMID 22040021, 2011). "The results revealed that CAFs were enriched in metastatic lung lesions and activated by tumor-derived WNT7A via the Wnt/β-catenin pathway." (PMID 42236896, 2026). "Consistently, a TCGA (The Cancer Genome Atlas) database analysis concluded that Wnt7a and Wnt7b levels correlate with the histological tumor differentiation of OSCC patients." (PMID 40421179, 2025). "Previous studies revealed that Wnt7a acts in a paracrine fashion through the canonical Wnt pathway by binding to receptor Frizzleds and activates β‐catenin signal in various tumours." (PMID 39834100, 2025). "likewise, IHC staing affirmed that the protein expression patterns of LY6D, MET, MUC16, and WNT7A were increased in tumor sample compared to healthy samples." (PMID 38169540, 2024). "We observed a positive correlation between tumor size and weight with the levels of WNT7A expression and Y705 phosphorylation of STAT3." (PMID 38246919, 2024).
tumor (continued). "While previous studies have shown that WNT7A promotes tumor progression through the Wnt-β-catenin pathway, our study found that it activates a previously undescribed STAT3-mediated noncanonical Wnt pathway in HNSCC." (PMID 38246919, 2024). "Knockdown of WNT7A resulted in significant inhibition of cell growth, colony formation and tumor-sphere formation in HNSCC cells." (PMID 38246919, 2024). "Our study found that WNT7A expression is correlated with tumor growth and survival rate in HNSCC, suggesting its potential use as a prognostic marker." (PMID 38246919, 2024). "A previous study has identified that tumor cell-derived Wnt7a recruits and activates fibroblasts to CAFs to promote tumor aggressiveness." (PMID 37065872, 2023). "In order to further prove that NE can regulate the expression level of WNT7A, we detected the expression levels of Wnt1, Wnt2, Wnt3a, Wnt4, Wnt5a, Wnt6, Wnt7a and Wnt10a in tumour tissues of anti-PD-1 mAb + Vehicle and NE + anti-PD-1 mAb + Vehicle groups." (PMID 36646807, 2023). "Whole-exome sequencing revealed 99 somatic mutations including SMARCA4, ARID2, TET2, CDKN2A, WNT7A, NOTCH3 and STAG2, all present both in the primary tumor and in the cell line." (PMID 38201285, 2023). "Some DEGs have been proved to play an important role in regulating tumor cell invasion ability such as WNT7A, VEGFA, EFEMP1, TRPV2, and FOXC2, whose expressions are consistent with the phenotype (see Results)." (PMID 35755807, 2022). "Wnt7a produced by cancer cells was previously demonstrated to recruit and activate fibroblasts and promote tumor aggressiveness of 4T1 cells." (PMID 36096830, 2022). "Immunostaining showed lower protein expression of Wnt7a, Wnt7b, Mmp7 and Ccnd2 in tumor tissues of the PRDX6 knockout group compared to the wild-type group." (PMID 36209344, 2022). "On the other hand, numerous studies reported WNT7a to exert anti-tumoral functions in different tumor entities." (PMID 35885035, 2022). "In this regard, although there have been reports that suggest that WNT7A is an oncoprotein, it has also been shown that loss of WNT7A expression is significantly associated with poor RFS in BRCA and it is also involved in tumor cell differentiation." (PMID 33912452, 2021). "DNAH5, LTF, and Ezrin were significantly increased in tumor tissues (p < 0.05), and WNT7A displayed a slight increase (p = 0.0669)." (PMID 35178403, 2021). "Real-time PCR confirmed that SHWNT7B and SHWNT7C effectively silenced WNT7A expression at the protein and mRNA levels.After culture with pellet forming medium, Wnt7A knockout reduced the number of tumor globules in HT29 and HT116 cells." (PMID 33791195, 2021). "Further analysis of the correlation between the WNT gene family and the clinicopathological parameters of UCEC showed that WNT7A was significantly different in different clinical stages, tumor grades, age groups, and histological types." (PMID 34565373, 2021). "Among 56 OSCC cases, the WNT7A expression in poorly differentiated tumor tissues was markedly increased compared with the expression in well-differentiated tumor tissues." (PMID 32174831, 2020). "The results indicated that the expression of WNT7A in tumor tissues was higher than that in matched adjacent tissues." (PMID 32174831, 2020). "In keeping with this finding, Avgustinova and colleagues demonstrated that tumour cell-derived Wnt7a recruits and activates fibroblasts to promote tumour aggressiveness both in vitro and in animals." (PMID 33260642, 2020). "During tumor progression, fibroblasts are transformed into activated fibroblasts called CAFs thanks to Transforming Growth Factor β1 (TGFβ1), Wnt7a, and other factors secreted by the tumor cells." (PMID 33322132, 2020). "Using online algorithms, we were able to predict potential miR-361 target genes involved in cancer metastasis, such as MEF2D, ROCK1 and WNT7A, and the tumor microenvironment, including KPNA4, PDE4B and VEGF-A." (PMID 31287002, 2019).
tumor (continued). "To further investigate the molecular mechanism by which Wnt7a plays its tumor-suppressive role, we detected the expression level of antioncogene P21." (PMID 31886205, 2019). "WNT7A, an important ligand of Wnt/β-catenin signaling pathways, has a controversial role in tumor development." (PMID 30361522, 2018). "To explore the role of WNT7A in tumor metastasis, we performed transwell assays and wound healing assays for cell migration ability." (PMID 30361522, 2018). "Then, multivariate Cox regression analysis demonstrated that WNT7A expression, tumor differentiation as well as lymph node metastasis were independent risks factors for PDAC patients." (PMID 30361522, 2018). "We performed IHC staining in PDAC TMA, the results confirmed the high expression of WNT7A in tumor tissue at protein level." (PMID 30361522, 2018). "We found that WNT7A expression dramatically increased in PDAC tissue compared with paired adjacent non-tumor tissue in GSE16515(p = 0.0399) and GSE28735(p = 0.0091)." (PMID 30361522, 2018). "The results suggested that WNT7A is remarkably increased in PDAC tissue compared to adjacent non-tumor tissue (p = 0.0091)." (PMID 30361522, 2018). "Tumor concentrations of vincristine were higher in Wnt tumors with the leaky BBB compared to the BBB from tumors engineered to express a Wnt7a agonist." (PMID 29186899, 2017). "In our future study, we intend to confirm our results in human tumor tissues, and we will further investigate the mechanism underlying the antitumor action of NOMAC by means of SUFU and Wnt7a gene knockdown in RL95-2 cells." (PMID 28640224, 2017). "In consistent with the mRNA levels, Western blotting analysis demonstrated that both of SUFU and Wnt7a expression were significantly upregulated in tumor tissues with NOMAC treatment (p < 0.01)." (PMID 28640224, 2017). "Strikingly, Wnt7a was as effective as TGFβ1 treatment in generating 4T07 tumours containing a substantial population of activated CAFs in the tumour core." (PMID 26777421, 2016). "Consistent with the initial set, tumours expressing high levels of Wnt7a have a significantly increased desmoplastic response, characterized by more numerous αSMA-positive CAFs (P=0.0576) as well as increased αSMA levels in the recruited CAFs (P=0.0009)." (PMID 26777421, 2016). "In organotypic assays in which tumour cells are plated on a 3D matrix containing live fibroblasts, Wnt7a treatment significantly enhances tumour cell invasion." (PMID 26777421, 2016). "As WNT7A activates tumor growth and progression in OvCa via the WNT7A/CTNNB1 signaling pathway, downregulation of miR-15b allows aberrant WNT7A expression is further support the impact of WNT7A and its mechanisms in OvCa." (PMID 27195958, 2016). "In light of our findings that Wnt7a promotes an altered stromal compartment in aggressive tumours, we next characterized the functional properties of Wnt7a-activated CAFs." (PMID 26777421, 2016). "Next, to assess the effect of manipulating tumour cell Wnt7a expression levels on the fibroblast compartment in vivo, CAF recruitment was assessed in tumours generated by orthotopic inoculation of 4T07 cells ectopically expressing Wnt7a (4T07-Wnt7a)." (PMID 26777421, 2016). "Together, these data highlight Wnt7a as a novel and highly potent tumour cell-secreted factor that is sufficient to drive conversion of fibroblasts into CAFs within the tumour microenvironment." (PMID 26777421, 2016). "On the other hand, the downregulation of Wnt7A gene expression was detected in the majority of ccRCCs, while methylation analysis revealed positive correlations between tumor stage and Wnt7A hypermethylation." (PMID 27322325, 2016). "In this study, we identified Wnt7a as a novel inducer of tumor-suppressive cellular senescence in the lung." (PMID 25728679, 2015). "Immunostaining was performed to evaluate the expression of ITGA9 and WNT7A proteins in three cases of NPC tumor cells and adjacent control nasopharyngeal epithelium." (PMID 26372814, 2015).